POLE3 (DNA polymerase epsilon 3, accessory subunit)
Description:
Accessory component of the DNA polymerase epsilon complex. Participates in DNA repair and in chromosomal DNA replication (By similarity). Forms a complex with CHRAC1 and binds naked DNA, which is then incorporated into chromatin, aided by the nucleosome-remodeling activity of ISWI/SNF2H and ACF1. Does not enhance nucleosome sliding activity of the ACF-5 ISWI chromatin remodeling complex.
Synonyms: CHRAC17; Ybl1; p17; CHARAC17; CHRAC2
Tractability: Small molecule: an approved drug acts on it. PROTAC: ubiquitination databases record sites on it; its protein half-life has been measured.
Gene: Protein-coding gene on chromosome 9 (113,407,232 to 113,410,723, reverse strand). Ensembl gene ENSG00000148229.
Subcellular location: Nucleus
Subcellular location (Human Protein Atlas): Nucleoplasm; Cytosol; Nucleoli
Pathways (Reactome):
DNA Repair: Dual Incision in GG-NER; Dual incision in TC-NER; Gap-filling DNA repair synthesis and ligation in GG-NER; Gap-filling DNA repair synthesis and ligation in TC-NER; HDR through Homologous Recombination (HRR); PCNA-Dependent Long Patch Base Excision Repair; Recognition of DNA damage by PCNA-containing replication complex; Termination of translesion DNA synthesis
DNA Replication: Activation of the pre-replicative complex; DNA replication initiation
Gene Ontology:
Molecular function: protein binding; chromatin DNA binding; DNA-directed DNA polymerase activity; protein heterodimerization activity
Biological process: chromatin remodeling; DNA-templated DNA replication; negative regulation of transcription by RNA polymerase II; nucleosome assembly; regulation of DNA replication; DNA damage response; DNA replication; heterochromatin formation; leading strand elongation; DNA biosynthetic process
Cellular component: ATAC complex; epsilon DNA polymerase complex; CHRAC; nucleoplasm; nucleus; chromatin
Genetic constraint (gnomAD): Loss-of-function variants: 8 observed, 12.55 expected, observed/expected ratio (o/e) 0.64, 90% interval 0.37 to 1.15. The upper end of that interval is the gene's LOEUF score, 1.15, which puts it in group 5 of 6, group 1 being the genes least tolerant of losing a copy. Missense variants: 147 observed, 157.21 expected, observed/expected ratio (o/e) 0.94, 90% interval 0.82 to 1.07. Synonymous variants: 77 observed, 63.74 expected, observed/expected ratio (o/e) 1.21, 90% interval 1 to 1.46.
Homologues: Orthologues: chimpanzee POLE3 (100% identical), macaque POLE3 (100% identical), dog POLE3 (99% identical), pig POLE3 (99% identical), guinea pig POLE3 (97% identical), rabbit POLE3 (96% identical), rat Pole3 (96% identical), mouse Pole3 (93% identical).
Diseases named in the same sentence as POLE3 in open-access papers:
POLE3 is named in the same sentence as 8 diseases in open-access papers, as found by Europe PMC text mining. Sharing a sentence is not in itself a finding about the gene and the disease. The quoted sentences say what the papers report.
Fanconi anemia (2 papers, 2022). Fanconi anemia (FA) is a hereditary DNA repair disorder characterized by progressive pancytopenia with bone marrow failure, variable congenital malformations and predisposition to develop hematological or solid tumors. "Besides ABCC4, POLE3, POLE4, and the Fanconi anemia pathway genes FANCF and C17orf70 are top candidates that sensitize both wild-type and TDP1-KO cells to CPT treatment." (PMID 35869071, 2022).
cervical cancer (1 paper, 2024). A primary or metastatic malignant neoplasm involving the cervix. "Previous studies have recognized POLE3, among 10 other genes, as hub genes for cervical cancer, with increased expression of POLE3 associated with the advancement of cervical cancer." (PMID 39085482, 2024).
pancreatic cancer (1 paper, 2020). "The transcription factors NFYC, TFDP3, POLE3 and E2F4 are closely linked to hub genes in pancreatic cancer." (PMID 32587798, 2020).
prostate carcinoma (1 paper, 2024). A carcinoma that arises from epithelial cells of the prostate gland. "However, investigations into the connection between POLE3 and the progression of prostate cancer (PCa) are scarce and warrant further exploration." (PMID 39085482, 2024).
cancer (5 papers, 2021 to 2023). A tumor composed of atypical neoplastic, often pleomorphic cells that invade other tissues. "The H3K36me3 eSPAN signals in POLE3 KO MCF-7 cells displayed a weak bias toward the lagging strand, indicating POLE3 KO also impairs the transfer of parental histones to leading strands in cancer cells." (PMID 37301892, 2023). "To further confirm the roles of parental histone inheritance in cancer cells, we deleted POLE3 in MCF-7 cell line by CRISPR­mediated knockout (KO) to investigate its impact on epigenetic reprogramming." (PMID 37301892, 2023). "ASFB1 expression was also associated with POLE3, CKS1B, and DHFR expression in most normal tissues and in many cancers including LUAD (R>0.4, p<0.05)." (PMID 34568067, 2021). "Our results reveal three important genes, HMGB1, APEX1, and POLE3, that function in the epigenetic control of a DNA-repair mechanism, which modulates cancer in HT29 cells, and induce apoptosis." (PMID 34500845, 2021). "In line with such a functional relationship, POLE3, POLE4, DSCC1, CHTF18, and CHTF8 show a high correlation in co-essentiality score across cell lines as determined by the Cancer Dependency Map database." (PMID 36622344, 2023).
tumor (5 papers, 2020 to 2023). "Lastly, POLE3, which is associated with the differentiation of lymphocyte-like cells, was inferred in NNMT+ tumor cells." (PMID 37430270, 2023). "Furthermore, the correlation between the dysregulated histone marks and their target proliferation-related genes in MCM2-2A mutant and POLE3 KO MCF-7 organoids further suggests the important role of impaired histone inheritance in tumor growth." (PMID 37301892, 2023). "Herein, we determined that in LUAD cells, ASF1B can indirectly regulate CKS1B, POLE3, and DHFR expression, and we found it positively correlated with the expression of these genes in most tumor and normal tissue samples." (PMID 34568067, 2021).
infection (1 paper, 2023). The state of being infected such as from the introduction of a foreign agent such as serum, vaccine, antigenic substance or organism. "HIV-LucIND116A infection of POLE3 KD primary CD4+ T cells resulted in an increased (2.3- to 4.5-fold) type I IFN response compared to that in noninfected and HIV-1 IND116A-infected control CD4+ T cells." (PMID 37922361, 2023). "We then generated HeLa cells with knockout (KO) of POLE3 and POLE4 using CRISPR-Cas9 gene editing and measured uHIV-1 DNA expression upon infection with HIV-Luc IND116A virus." (PMID 37922361, 2023). "Unexpectedly, after infection at both MOIs, HIV-1 replication kinetics were markedly impaired in HeLa-P4 POLE3 KO cells and delayed in SupT1 POLE3 KD cells compared to control cells." (PMID 37922361, 2023). "Similarly, in the absence of infection, POLE3 KD resulted in low but significant induction of the IFN response compared to that in siNT control cells, suggesting a role of POLE3 in regulating the innate immune response." (PMID 37922361, 2023).
POLE3 also shares sentences with these, for which no sentence is quoted: heart failure (1 paper).